RUNX3 (RUNX family transcription factor 3)
Description:
Forms the heterodimeric complex core-binding factor (CBF) with CBFB. RUNX members modulate the transcription of their target genes through recognizing the core consensus binding sequence 5'-TGTGGT-3', or very rarely, 5'-TGCGGT-3', within their regulatory regions via their runt domain, while CBFB is a non-DNA-binding regulatory subunit that allosterically enhances the sequence-specific DNA-binding capacity of RUNX. The heterodimers bind to the core site of a number of enhancers and promoters, including murine leukemia virus, polyomavirus enhancer, T-cell receptor enhancers, LCK, IL3 and GM-CSF promoters (By similarity). May be involved in the control of cellular proliferation and/or differentiation. In association with ZFHX3, up-regulates CDKN1A promoter activity following TGF-beta stimulation. CBF complexes repress ZBTB7B transcription factor during cytotoxic (CD8+) T cell development. They bind to RUNX-binding sequence within the ZBTB7B locus acting as transcriptional silencer and allowing for cytotoxic T cell differentiation. CBF complexes binding to the transcriptional silencer is essential for recruitment of nuclear protein complexes that catalyze epigenetic modifications to establish epigenetic ZBTB7B silencing (By similarity). Necessary for the development and survival of sensory neurons expressing parvalbumin (By similarity).
Synonyms: AML2; CBFA3; PEBP2A3; PEBP2aC
Tractability: PROTAC: UniProt records ubiquitination sites on it; ubiquitination databases record sites on it; its protein half-life has been measured.
Gene: Protein-coding gene on chromosome 1 (24,899,511 to 24,965,121, reverse strand). Ensembl gene ENSG00000020633.
Subcellular location: Nucleus; Cytoplasm
Subcellular location (Human Protein Atlas): Nucleoplasm; Vesicles; Cytosol
Pathways (Reactome):
Gene expression (Transcription): RUNX3 Regulates Immune Response and Cell Migration; RUNX3 regulates BCL2L11 (BIM) transcription; RUNX3 regulates CDKN1A transcription; RUNX3 regulates NOTCH signaling; RUNX3 regulates RUNX1-mediated transcription; RUNX3 regulates WNT signaling; RUNX3 regulates YAP1-mediated transcription; RUNX3 regulates p14-ARF; Regulation of RUNX3 expression and activity
Developmental Biology: Differentiation of naive CD4+ T cells to T helper 1 cells (Th1 cells)
Signal Transduction: Binding of TCF/LEF:CTNNB1 to target gene promoters
Gene Ontology:
Molecular function: protein binding; sequence-specific double-stranded DNA binding; transcription corepressor binding; ATP binding; DNA-binding transcription factor activity; DNA-binding transcription factor activity, RNA polymerase II-specific; RNA polymerase II cis-regulatory region sequence-specific DNA binding; RNA polymerase II transcription regulatory region sequence-specific DNA binding; DNA binding
Biological process: positive regulation of DNA-templated transcription; protein phosphorylation; regulation of transcription by RNA polymerase II; response to transforming growth factor beta; chondrocyte differentiation; hemopoiesis; negative regulation of CD4-positive, alpha-beta T cell differentiation; negative regulation of cell cycle; negative regulation of epithelial cell proliferation; negative regulation of transcription by RNA polymerase II; neuron differentiation; ossification; peripheral nervous system neuron development; positive regulation of CD8-positive, alpha-beta T cell differentiation; regulation of cell differentiation; regulation of DNA-templated transcription
Cellular component: core-binding factor complex; cytoplasm; cytosol; nucleoplasm; nucleus; chromatin
Genetic constraint (gnomAD): Loss-of-function variants: 9 observed, 22.49 expected, observed/expected ratio (o/e) 0.4, 90% interval 0.24 to 0.7. The upper end of that interval is the gene's LOEUF score, 0.7, which puts it in group 2 of 6, group 1 being the genes least tolerant of losing a copy. Missense variants: 464 observed, 538 expected, observed/expected ratio (o/e) 0.86, 90% interval 0.8 to 0.93. Synonymous variants: 267 observed, 230.31 expected, observed/expected ratio (o/e) 1.16, 90% interval 1.05 to 1.28.
Homologues: Orthologues: chimpanzee RUNX3 (99% identical), macaque RUNX3 (98% identical), pig RUNX3 (97% identical), dog RUNX3 (93% identical), guinea pig RUNX3 (91% identical), mouse Runx3 (91% identical), rat Runx3 (91% identical), tropical clawed frog runx3 (76% identical), zebrafish runx3 (68% identical), Drosophila melanogaster run (33% identical), Caenorhabditis elegans rnt-1 (27% identical). Paralogues in human: RUNX1 (65% identical), RUNX2 (65% identical).
Diseases named in the same sentence as RUNX3 in open-access papers:
RUNX3 is named in the same sentence as 246 diseases in open-access papers, as found by Europe PMC text mining. Sharing a sentence is not in itself a finding about the gene and the disease. The quoted sentences say what the papers report.
gastric cancer (158 papers, 2004 to 2025). A primary or metastatic malignant neoplasm involving the stomach. "The R122C mutation was identified in human gastric cancer patients and represents a clinically relevant alteration that impairs RUNX3 DNA-binding activity, making this model more representative of human disease than complete knockout models." (PMID 40673273, 2025). "The expansion of isthmus stem/progenitor cells reflects the stem cell dysfunction observed in human gastric cancer, where RUNX3 loss disrupts normal epithelial differentiation and promotes a more primitive, proliferative phenotype." (PMID 40673273, 2025). "Initially, the gastric phenotype of Runx3-knockout mice and the cause-and-effect relationship between loss of RUNX3 and human gastric cancer development suggested that RUNX3 acts as a tumor suppressor." (PMID 37190031, 2023). "We previously identified the RUNX3 single missense mutation R122C from a human gastric cancer patient." (PMID 36766749, 2023). "Through the detection of plasma samples, RUNX3 methylation level was considered to be a risk factor for gastric cancer metastasis and a potential indicator of gastric cancer progression." (PMID 35721189, 2022). "RUNX3 has been associated with gastric cancer and other types of cancers—for example, lung, breast, and pancreatic cancers." (PMID 36231060, 2022). "The depletion of Runx3 is a cause of gastric cancer development, and evidence that inactivation of Runx3 expression or function is a key event in gastric cancer and many other types of cancer has accumulated." (PMID 33672337, 2021). "Binominal logistic regression analysis showed that age, gender, the severity of endoscopic gastric atrophy, and methylated RUNX3 level were independent risk factors for gastric cancer." (PMID 32224873, 2020). "Studies have indicated a tumor-suppressing role of RUNX3 and complete inactivation or downregulation of RUNX3 gene has been associated with gastric cancer, CaEs pancreatic cancer." (PMID 32943993, 2020). "We found a significant association between increased numbers of methylated RUNX3 copies and lymph-vascular invasion and tumor size in early gastric cancer." (PMID 32224873, 2020). "The study of loss of RUNX3 expression during progression to invasive gastric cancer compared to the normal gastric epithelium was the first suggesting tumour suppressive function for RUNX3." (PMID 31467531, 2019). "RUNX3 was first reported as a tumor suppressor in gastric cancer because of the causal link between the loss of RUNX3 and gastric carcinogenesis." (PMID 27825140, 2017). "The RUNX3 tumor suppressor was associated with gastric cancer development about a decade ago, and has since been reported as inactivated in various types of invasive and pre-invasive epithelial and mesenchymal tumors." (PMID 29254144, 2017). "This shows that RUNX3 methylation is age related and its silencing is associated with advanced stage of gastric cancer." (PMID 28144288, 2017). "Aberrantly methylated RUNX3 was found to be associated with the risk of multiple cancers, such as hepatocellular carcinoma, esophageal cancer, gastric carcinoma and NSCLC." (PMID 26862903, 2016). "We focused on RUNX3 and Smad4 since it has been previously shown that RUNX3 and Smad4 as tumor suppressor genes are associated with gastric cancer." (PMID 26134263, 2015). "Runt-related transcription factor 3 (RUNX3) has been implicated in gastric cancer, although mutations in this gene are rare." (PMID 25997695, 2015). "RUNX3 is a tumor suppressor in gastric cancer and inactivation of RUNX3 is causally associated with human gastric carcinogenesis." (PMID 26375442, 2015).
gastric cancer (continued). "Based on their results, tumorigenicity of human gastric cancer-derived cells was inversely correlated with RUNX3 expression level and mutation within the genomic region encoding Runt domain of RUNX3 (R122C) abrogated its tumor suppressive activity." (PMID 26512706, 2015). "Recent findings showed that, RUNX3 and Smad4, which function as tumor-suppressor genes, are associated with gastric cancer." (PMID 26134263, 2015). "Clinical studies demonstrated that loss of RUNX3 expression is associated with gastric cancer progression and poor prognosis, but the underlying mechanism is not entirely clear." (PMID 24447545, 2014). "Although RUNX3 is infrequently mutated in various human cancers, R122C mutation found within its conserved runt domain, which was identified in a gastric cancer patient, abolished the tumor-suppressive function of RUNX3 in nude mice." (PMID 24078903, 2013). "RUNX3 methylation was also associated with histological type and differentiation state of the gastric cancer." (PMID 21867527, 2011). "We therefore conducted a meta-analysis using all available related studies to better define the association between RUNX3 promoter methylation and gastric cancer." (PMID 21867527, 2011). "This meta-analysis identified a strong association between methylation of the RUNX3 promoter and gastric cancer, confirming the role of RUNX3 as a tumor suppressor gene." (PMID 21867527, 2011). "The pooled OR was 4.67 (95%CI: 2.57, 8.49; P < 0.0001) indicating a positive association between RUNX3 methylation and gastric cancer." (PMID 21867527, 2011). "A significant association was observed between RUNX3 promoter methylation and gastric cancer, with an aggregated odds ratio (OR) of 5.63 (95%CI 3.15, 10.07)." (PMID 21867527, 2011). "The overall OR of the trim and fill method was 4.67, which was slightly smaller than that of the crude meta-analysis, but it was still significant, indicating a strong association between RUNX3 promoter methylation and gastric cancer." (PMID 21867527, 2011). "We therefore performed a meta-analysis to quantify the association between RUNX3 promoter methylation and gastric cancer." (PMID 21867527, 2011). "In conclusion, this meta-analysis of pooled data provides additional evidence to support a strong association between methylation of the RUNX3 promoter and gastric cancer." (PMID 21867527, 2011). "In human gastric cancers, hypermethylation of RUNX3, hemizygous deletion and truncating point mutations have been observed." (PMID 18551179, 2008). "In this study, the CpG island of the RUNX3 gene was specifically methylated in the LOH-B gastric cancers, which were associated with diffuse-type cancers without forming well-defined glandular structures." (PMID 16827945, 2006). "Our previous studies suggest that lack of RUNX3 function is causally related to the genesis and progression of human gastric cancer, indicating that RUNX3 is a novel tumour suppressor." (PMID 15685235, 2005). "Our previous studies suggest that a lack of RUNX3 function is causally related to the genesis and progression of human gastric cancer." (PMID 15685235, 2005). "However, increased RUNX3 expression has been linked to a poor prognosis in gastric cancer in multiple investigations." (PMID 35522574, 2022). "For example, Helicobacter pylori infection, a primary cause of gastric cancer, could lead to promoter hypermethylation of many tumor suppressor genes, including RUNX3." (PMID 36429115, 2022). "Moreover, the loss or decreased expression of RUNX3 has been associated with a poorer survival rate in gastric cancer." (PMID 32651460, 2020).
gastric cancer (continued). "RUNX3 was well identified to function as a tumour suppressor, and its inactivation was associated with tumorigenesis in lung adenocarcinoma, intestinal adenocarcinoma, colorectal cancer and gastric cancer." (PMID 32307917, 2020). "In contrast to the other RUNX family members such as RUNX1 and RUNX3 whose mutations are tightly linked to the promotion of leukemia and gastric cancer, respectively, the initial studies strongly suggest that RUNX2 acts as a master regulator of osteoblast differentiation and bone development." (PMID 29558908, 2018). "Unexpectedly, RUNX3 is rarely mutated in primary gastric cancer tissues." (PMID 26512706, 2015). "Importantly, the decrease in RUNX3 protein expression is significantly associated with decreased survival of gastric cancer and melanoma patients." (PMID 23457532, 2013). "Since RUNX3-deficient mice displayed hyperplasia in gastric mucosa caused by reduced apoptosis and the stimulated growth of the gastric epithelial cells, RUNX3 has been considered to be a tumor suppressor for human gastric cancer." (PMID 24078903, 2013). "Previous findings showed that, RUNX3 was identified as a pivotal tumor-suppressor in gastric cancer, and a loss or substantial decrease in RUNX3 expression may be causally associated with gastric cancer, as it correlates with differentiation, lymph node metastasis and poor prognosis of this disease." (PMID 26134263, 2015). "For instance, miR-17-5p has been shown to directly target RUNX3 in gastric cancer (GC), leading to enhanced cell proliferation and invasion." (PMID 40167762, 2025). "This activation can lead to the downregulation of downstream tumor suppressor genes like Gastrokine1 (GKN1) and Runt-related transcription factor 3 (Runx3), ultimately promoting abnormal proliferation and invasion in gastric cancer." (PMID 40654572, 2025). "RUNX3 acts as a tumor suppressor in gastric cancer, colon cancer, and some other solid tumors, but it is usually inactivated during tumor progression due to loss of heterozygosity, promoter hypermethylation, histone modification, and protein mislocalization." (PMID 38430423, 2024). "A better understanding of RUNX3 regulation of WNT5A will yield insights to treatment of late-stage gastric cancer." (PMID 38240752, 2024). "Subversion of RUNX3 developmental gene targets to metastasis program indicates the oncogenic nature of inappropriate RUNX3 regulation in gastric cancer." (PMID 38240752, 2024). "Inhibition of RUNX3 in gastric cancer cell lines reduced migration, invasion, and anchorage-independent growth in vitro." (PMID 38240752, 2024). "Silencing of RUNX3 expression by hypermethylation of the CpG island in the RUNX3 P2 promoter was detected in diverse cancer types, including gastric cancer." (PMID 38240752, 2024). "Here, we show that RUNX3 promotes cell migration, invasion, and anchorage-independent growth of gastric cancer cells in vitro and promotes tumor growth and metastasis in vivo." (PMID 38240752, 2024). "Another study showed that, upon stimulation with TGF-β, ATBF1 bound the transcription factor RUNX3, resulting in cotranslocation to the nucleus and synergistic upregulation of p21Waf1/Cip1 promoter activity in gastric cancer cells." (PMID 38227369, 2024). "To explore the effects of RUNX3 on metastatic potential, we conducted siRNA-mediated KD of RUNX3 in RUNX3-expressing gastric cancer cell lines, such as HGC-27 and LMSU." (PMID 38240752, 2024). "We interrogated the potential of RUNX3 as a metastasis driver in gastric cancer by profiling its target genes." (PMID 38240752, 2024). "In gastric cancer, RUNX3 is targeted and suppressed by miR-106a, particularly in multidrug-resistant (MDR) cell lines." (PMID 38430423, 2024).